BRD4 (bromodomain containing 4)
Diseases named in the same sentence as BRD4 in open-access papers (continued):
Sharing a sentence is not in itself a finding about the gene and the disease.
pancreatic cancer (continued). "It has been reported that PES1 interacts with BRD4 to enhance c-Myc expression, thereby promoting cell growth and cell resistance to extra-terminal inhibitors in pancreatic cancer." (PMID 34782005, 2021). "Taken together, these results suggest that BRD4 upregulates GDF15 by inducing NR5A2 expression in pancreatic cancer cells." (PMID 33850096, 2021). "We further identified that NR5A2 was transcriptionally upregulated by BRD4 in pancreatic cancer cells and this was confirmed by Chromatin immunoprecipitation (ChIP) and ChIP-qPCR." (PMID 33850096, 2021). "Taken together, these results demonstrate that BRD4 transcriptionally activates NR5A2 expression in pancreatic cancer." (PMID 33850096, 2021). "In this study, we identified BRD4 as a transcriptional activator of NR5A2 in pancreatic cancer cells and provided another viable strategy to target oncogenic NR5A2." (PMID 33850096, 2021). "We have previously shown that aberrant expression of histone acetyltransferase 1 (HAT1) enhanced PD-L1 expression and promoted pancreatic cancer cell proliferation by modulating the function of BRD4." (PMID 34564701, 2021). "This study aims to analyze the effect of BRD4 on the cell growth and progression of pancreatic cancer and novel mechanisms involved." (PMID 32099528, 2020). "Our findings reveal the oncogenic effects of BRD4 in pancreatic cancer and elucidate a possible mechanism by which BRD4 and caveolin-2 act to enhance cell growth." (PMID 32099528, 2020). "The next study will focus on the molecular mechanism by which BRD4 regulates metastasis in pancreatic cancer." (PMID 32099528, 2020). "BRD4 (high)/caveolin-2 (high) correlated with shorter overall survival of patients with pancreatic cancer." (PMID 32099528, 2020). "INBC057643 was developed as a BRD inhibitor, and it reduced cell proliferation and increased expression of p27, indicative of cell cycle arrest, in several murine and human pancreatic cancer lines, as has been reported for other BRD4 inhibitors." (PMID 33396954, 2020). "Targeting the BRD4-caveolin-2 interaction by development of BET inhibitors will be a therapeutic strategy for pancreatic cancer." (PMID 32099528, 2020). "LINC00346 has sequestered miR-188-3p and obstructed the suppression of BRD4 by miR-188-3p in pancreatic cancer cells." (PMID 32514489, 2020). "We found that overexpression of BRD4 almost completely blocked the chemosensitizing effect on pancreatic cancer cells induced by LINC00346 depletion." (PMID 30728036, 2019). "Since BRD4 is involved in the growth and gemcitabine chemoresistance of pancreatic cancer cells, we suggest that LINC00346 promotes aggressiveness of pancreatic cancer cells by sponging miR-188-3p and inducing BRD4." (PMID 30728036, 2019). "Given the connections between c-Myc, PES1, and BET inhibitors, we explored the possibility of an interaction between PES1 and BRD4 in pancreatic cancer cells." (PMID 31718704, 2019). "Most interestingly, LINC00346 overexpression abrogates miR-188-3p-mediated repression of BRD4 in pancreatic cancer cells." (PMID 30728036, 2019). "Taken together, LINC00346 has the ability to mask BRD4 from miR-188-3p-dependent repression in pancreatic cancer." (PMID 30728036, 2019). "Given co-expression of hnRNPA1 and the BET protein BRD4 in human thyroid and pancreatic tumors, and the favorable safety profiles of Quercetin and BET inhibitors, our study provides a rationale for pursuing this combination therapy in advanced cancer patients." (PMID 31480735, 2019). "We found that silencing of BRD4 significantly inhibited the proliferation and colony formation of pancreatic cancer cells stably expressed LINC00346." (PMID 30728036, 2019). "This argument is supported by the finding that knockdown of BRD4 significantly prevents LINC00346-induced pancreatic cancer growth." (PMID 30728036, 2019). "We also demonstrated that PES1 bound to BRD4 to increase c-Myc expression in pancreatic cancer cells." (PMID 31718704, 2019).
pancreatic cancer (continued). "The in vivo loss of KDM6A enhances gender-specific squamous-like pancreatic cancer, as an X-chromosomal gene via super-enhancer activation can be targeted with a BET inhibitor via KDM6A loss-regulated BRD4 function." (PMID 31238554, 2019). "Collectively, our data suggest that PES1 interacted with BRD4 and initiated the transcription of Myc in pancreatic cancer cells." (PMID 31718704, 2019). "Mechanistic investigation revealed that LINC00346 acted as a sponge for miR-188-3p and blocked the repression of BRD4 by miR-188-3p in pancreatic cancer cells." (PMID 30728036, 2019). "LINC00346 shows the ability to promote pancreatic cancer growth and gemcitabine resistance, which is in part mediated by antagonization of miR-188-3p and induction of BRD4." (PMID 30728036, 2019). "The endogenous level of BRD4 in pancreatic cancer cells was also decreased by miR-188-3p overexpression." (PMID 30728036, 2019). "Strikingly, we showed that HAT1 transcriptionally regulated PD-L1, and this process was mainly mediated by BRD4 in pancreatic cancer." (PMID 30709380, 2019). "Increased expression of BRD4 is noted in pancreatic cancer, and targeted reduction of BRD4 leads to inhibition of cancer growth." (PMID 30728036, 2019). "We show that the CD18 pancreatic cancer cells developing resistance to JQ1 are resistant to BRD4 knockdown and maintain or increase expression of JQ1-target genes." (PMID 25807524, 2015). "In pancreatic cancer, it has been shown to be controlled by BRD4 and to contribute to cell growth." (PMID 39994275, 2025). "B7-H3 is transcriptionally regulated by BRD4 in pancreatic cancer cells, and targeting the BRD4/B7-H3/TLR4 axis may be a novel therapeutic strategy to overcome chemotherapy resistance in pancreatic cancer." (PMID 36499340, 2022). "Indeed, BRD4 overexpression in pancreatic cancer cells increased GDF15 expression at both the mRNA and protein levels; this effect was reversed by NR5A2 silencing." (PMID 33850096, 2021). "In addition, we showed that the expression of NR5A2 in pancreatic cancer cells was regulated by BRD4." (PMID 33850096, 2021). "Besides, we have previously shown that HAT1 promoted PD-L1 expression in pancreatic cancer cells in a BRD4-dependent manner." (PMID 34564701, 2021). "We have previously shown that HAT1 was overexpressed in pancreatic cancer and that HAT1 silencing reduced the expression of PD-L1 on the surface of pancreatic cancer cells in a BRD4-dependent manner, improve the therapeutic efficacy of immune checkpoint blockade." (PMID 34564701, 2021). "Therefore, after injury-induced chromatin changes, the BRD4-dependent transcriptional reprogramming is a key downstream event in pancreatic cancer initiation." (PMID 34023857, 2021). "Notably, BRD4 inhibition in pancreatic cancer downregulated GDF15 at the mRNA and protein levels, and GDF15 expression was recovered by NR5A2 silencing." (PMID 33850096, 2021). "Furthermore, we showed that PES1 interacted with BRD4 to enhance c-Myc expression, which is the primary cause of cancer cell resistance to BET inhibitors in pancreatic cancer." (PMID 31718704, 2019). "Besides, it has been reported that CD44, c-Jun, and BRD4 promote pancreatic cancer cell proliferation and metastasis and induce chemotherapy resistance." (PMID 31718704, 2019). "Moreover, ectopic expression of miR-188-3p significantly inhibits the expression of BRD4 in pancreatic cancer cells." (PMID 30728036, 2019). "In addition, silencing of BRD4 significantly inhibited LINC00346-induced pancreatic cancer cell proliferation and colony formation." (PMID 30728036, 2019).
pancreatic cancer (continued). "Hence, we hypothesized that BRD4 upregulated GDF15 by inducing NR5A2 expression in pancreatic cancer." (PMID 33850096, 2021). "Given our findings that BRDT colocalized with ΔNp63 on several genes such as FAT2 and PTHLH, which we previously demonstrated as being associated with ΔNp63-dependent SEs in pancreatic cancer, we investigated whether BRDT, like BRD4, may be a defining feature of SEs in a subset of ESCC." (PMID 33658703, 2021). "In addition, B7-H3 was transcriptionally regulated by BRD4 in pancreatic cancer cell." (PMID 31974361, 2020). "Additionally, we found that PES1 transcriptionally increased the expression of c-Myc in pancreatic cancer cells through interaction with BRD4, and PES1 might function as an activator to enhance BRD4 activity in pancreatic cancer cells." (PMID 31718704, 2019). "Using patient-derived xenografts of KRAS- and MYC-driven pancreatic carcinoma, we show that coinhibition of topoisomerase 1 (TOP1) and bromodomain-containing protein 4 (BRD4) synergistically induces tumor regression by targeting promoter pause release." (PMID 37831776, 2023). "Consistently, BRD4 silencing profoundly decreased NR5A2 expression on mRNA and protein levels in pancreatic cancer cells." (PMID 33850096, 2021). "Our data are in line with previous reports showing that inhibition of BRD4 restrains HH/GLI-dependent growth of medulloblastoma, BCC, breast and pancreatic cancers." (PMID 33958721, 2021). "This regulatory mechanism is similar to what we have previously shown for BRD4, the closest paralog to BRDT, which localizes to lineage-specific enhancers to regulate genes that are crucial for lineage specification and pancreatic cancer subtype." (PMID 33658703, 2021). "NR5A2 overexpression induced by BRD4 enhanced the transcription of GDF15 in pancreatic cancer, suggesting that BRD4/NR5A2/GDF15 axis is a potential therapeutic target in pancreatic cancer." (PMID 33850096, 2021). "We also revealed that PES1 interacted with BRD4 and contributed to cancer cell resistance to BET inhibitors by increasing the expression levels of c-Myc in pancreatic cancer." (PMID 31718704, 2019). "We have shown that pancreatic cancer cells developing resistance to JQ1 were also resistant to other BET inhibitors and to BRD4 down regulation." (PMID 27283767, 2016). "In contrast to the resistance mechanism identified in pancreatic cancer and leukemia cells, TNBC cells developing resistance to BET inhibitors continue to rely on BRD4 for ongoing proliferation." (PMID 27283767, 2016). "Significantly, targeting GLI2 re-sensitized pancreatic cancer cells to BET inhibitors and BRD4 down regulation." (PMID 27283767, 2016). "Here we show that pancreatic cancer cells developing resistance to JQ1 demonstrate cross-resistance to I-BET151 and insensitivity to BRD4 downregulation." (PMID 25807524, 2015). "Together, these results suggest that targeting transcription via dual inhibition of TOP1 and BRD4 can specifically target KRAS- and MYC-driven pancreatic tumors and provide viable and clinically applicable therapy for hard-to-treat cancer entities such as PDAC and panNEC." (PMID 37831776, 2023). "TOP1 and BRD4 drugs synergize to kill pancreatic cancer in vivo via readthrough transcription without emergent drug resistance." (PMID 37831776, 2023). "Furthermore, analysis using GEPIA indicated a strong positive correlation between BRD4 and PVT1 levels in pancreatic cancer specimens." (PMID 34564701, 2021). "Expression of BRD4 in pancreatic cancer and paired adjacent noncancerous tissues from 76 patients was analyzed by western blotting, immunohistochemistry, and real time PCR." (PMID 32099528, 2020). "In this study, we showed that NR5A2 promoted pancreatic cancer progression by inducing GDF15 expression, suggesting that the pro-tumorigenic roles of NR5A2 and BRD4 in pancreatic cancer could be reversed by GDF15 inhibition, making GDF15 a promising therapeutic target." (PMID 33850096, 2021).
pancreatic cancer (continued). "Furthermore, this work suggests that BRD4 may play a role in establishing the TME in the liver, a primary metastatic site for pancreatic cancer." (PMID 33396954, 2020). "Moreover, we found that BET inhibitors (JQ1) impeded the interaction between PES1 and BRD4 or the bromodomain of BRD4 (BD1 and BD2) in pancreatic cancer cells, which suggested that PES1 might bind to the bromodomain of BRD4." (PMID 31718704, 2019). "Dual blockade of SMO and BRD4 might also contribute to prevent resistance to pan-selective BET inhibitors such as JQ1, because resistance to JQ1 can be mediated by GLI2-dependent upregulation of cMYC and targeting GLI2 restores JQ1 sensitivity in pancreatic cancer." (PMID 33958721, 2021).
glioma (36 papers, 2017 to 2026). A benign or malignant brain and spinal cord tumor that arises from glial cells (astrocytes, oligodendrocytes, ependymal cells). "Although BRD4 clearly influences glioma progression and modulates key oncogenic pathways, the precise mechanisms underlying BRD4-driven gliomagenesis remain only partially understood." (PMID 41828493, 2026). "BRD4 has been implicated previously as a driver of glioma progression, potentially through promotion of MYC-driven anabolic pathways." (PMID 41187221, 2025). "Abnormal expression and dysfunction of BRD4 can be associated with the development of multiple cancers, and BRD4 is significantly associated with gliomas." (PMID 41353556, 2025). "JQ-1 suppresses the c-Myc transcription of BT142 cells (IDH mutated) via inhibition of BRD4.JQ-1 plus siBRD4 induces cell cycle arrest and apoptosis in glioma cells through down-regulation of VEGFR/PI3K/AKT signaling." (PMID 38786726, 2024). "Overall, these data suggest that BRD4 enhances malignancy primarily in gliomas bearing IDHmut and is associated with greater sensitivity to BET inhibition." (PMID 35467128, 2022). "We identified that high BRD4 expression associated with decreased survival only in IDHmut glioma patients." (PMID 35467128, 2022). "We delved in the association between BRD4 expression and histology of glioma in the genomic datasets." (PMID 33135348, 2020). "In both databases, BRD4 mRNA is inversely associated with OS in glioma patients." (PMID 33135348, 2020). "Recent advances have enabled the development of selective BRD4 inhibitors and degraders capable of penetrating the blood-brain barrier and preferentially targeting glioma cells." (PMID 41828493, 2026). "Among BET family members, BRD4 plays a notable role in glioma progression and malignancy, particularly in R132H IDH mutants, where MYC activation is associated with transformation into higher-grade GBMs." (PMID 40565099, 2025). "An in vitro assay revealed that SPP-ARV-825 significantly inhibited glioma cell proliferation, induced G0/G1 cell cycle arrest, and triggered apoptosis through BRD4 degradation compared to free ARV-825." (PMID 40284496, 2025). "And the ARV‐825, as a BRD4 PROTAC, requires minimal doses to efficiently degrade target proteins and exhibits reduced susceptibility to drug resistance in single‐agent glioma treatments." (PMID 39544152, 2024). "Thereupon, western blot analysis was further performed to confer the correlation between BRD4 and Notch1 protein expression after glioma cells were treated for 48 h." (PMID 39544152, 2024). "The results were basically consistent with the previous transcriptome sequencing analysis and real time qPCR analysis results, substantiating the positive correlation between Notch1 gene and BRD4 protein in glioma." (PMID 39544152, 2024). "JQ-1, a pan-inhibitor of bromodomain and extra-terminal (BET) proteins such as the epigenetic readers BRD2, BRD3, and BRD4, exerts a cytotoxic effect on BT142 glioma cells with mutated IDH, by inhibiting BRD4 and c-Myc downregulation." (PMID 38786726, 2024). "Two BET proteins, BRD2 and BRD4, are significantly overexpressed in gliomas, and the knockout of BRD4 diminishes glioma proliferation." (PMID 38183103, 2024). "One study used the bromodomain inhibitor, JQ1, to prevent BET protein binding and activity, allowing for the impact of BRD4 in glioma stem cells to be investigated." (PMID 38183103, 2024). "BRD4 is positively correlated with massively infiltrated glioma macrophages, and high expression of the BRD4 gene and TAM2 is linked with poor prognosis in glioma patients." (PMID 36599655, 2023). "BRD4 facilitates glioma stem cell (GSC) properties through VEGF/PI3K/AKT signaling, and small molecule inhibitor JQ1 significantly inhibited the self-renewal of GSCs." (PMID 36674511, 2023).